Y_RNA (Y RNA )
Gene: Miscellaneous RNA gene on chromosome X (107,202,577 to 107,202,683, forward strand). Ensembl gene ENSG00000199832.
Homologues: Orthologues: chimpanzee Y_RNA (97% identical). Paralogues in human: Y_RNA (82% identical), Y_RNA (81% identical), RNY3 (80% identical), RNY3P1 (80% identical), Y_RNA (80% identical), Y_RNA (79% identical), RNY3P7 (78% identical), Y_RNA (78% identical), Y_RNA (77% identical), Y_RNA (76% identical), RNY3P14 (75% identical), RNY3P16 (75% identical), and 92 more.